ZEB1 (zinc finger E-box binding homeobox 1)
Diseases named in the same sentence as ZEB1 in open-access papers (continued):
Sharing a sentence is not in itself a finding about the gene and the disease.
cancer (continued). "Interestingly, expression of the EMT regulator Twist was also unaltered in 1LM and 2LM cells, and the TWIST-Slug-ZEB1 metastatic correlation appeared to be biologically relevant in the invasion of cancer cells but not MDA-MB-231 cells." (PMID 29163048, 2017). "Thus, apart from its general role as an EMT inducer, ZEB1 and ZEB2 may have multiple functions that will be elucidated by analyses in specific cancer types in the future." (PMID 28618162, 2017). "These factors may functionally activate EMT-inducing transcription factors, such as Snail (SNAI1), Slug (SNAI2), zinc finger E-box binding homeobox 1 (ZEB1), Twist family BHLH Transcription Factor 1 (Twist), Goosecoid (GSC), and forkhead box protein C2 (FOXC2) in cancer cells." (PMID 27270649, 2016). "The ZEB1/miR-200 axis likely has additional, non-cell autonomous roles in cancer pathogenesis, as it has recently been shown to affect immune recognition of cancer cells whereby ZEB1 suppression of the miR-200 family leads to upregulation of PD-L1, a direct miR-200 family target." (PMID 27317311, 2016). "Based on these results, our current model is that the upregulation of ZEB1 has a positive effect on viral latency maintenance and, alone or together with the increase of other 3 ́-UTR ARE-containing oncogenes, promotes cell proliferation, ultimately producing cancer." (PMID 26121143, 2015). "Furthermore, the expression levels of phosphorylated AKT, phosphorylated GSK3β, ZEB-1 and snail-1, all of which are very important for EMT process during cancer progression, were significantly up regulated in Rab3D-MCF-7 cells, but decreased in siRab3D-MDA-MB-231 cells." (PMID 25823663, 2015). "In addition, there was marked elevation in expression levels of established biomarkers of EMT (i. e. zeb1; vimentin; snail; and slug) parallels similar cellular and molecular changes by which aberrant RANK signaling accelerates the progression of cancers to advanced stage disease." (PMID 26061636, 2015). "In addition, several components of TGF-b signaling pathways, TGFBR2, Snail and ZEB1, were reduced directly or indirectly by overexpression of miR-655 in cancer cells treated with or without TGF-b." (PMID 23690952, 2013). "Next we investigated whether the negative correlation between Zeb1 paralogs and epcam expression observed in zebrafish also holds true in cellular cancer models." (PMID 23667256, 2013). "Taken together, the elevated ZEB1 expression following EMT may serve as an important mediator that could converge highly activated EGFR-MEK/ERK signaling on MMP2 induction, facilitating the invasion of the EMT-induced cancer cells." (PMID 24318272, 2013). "The present study is the first to show clearly that miR-655 targets ZEB1 and TGFBR2 inducing inactivation of the TGF-b signaling pathway, involving the miR-200-ZEB1-E-cadherin axis, strongly suggesting a potential role for miR-655 as a prognostic marker and therapeutic agent in human cancers." (PMID 23690952, 2013). "Given the critical role of Akt, ZEB1, and ZEB2 in cancer progression, the findings from this study provide additional novel evidence that Akt activation may play an important role in arsenic lung carcinogenesis by promoting As-transformed HBEC migration and invasion." (PMID 21954225, 2012). "It remains to be clarified whether breast epithelial tumor cells per se do not express zeb1 even in hormone positive carcinomas." (PMID 21324165, 2011). "Mooney and co-workers showed that key regulators of EMT (e.g., ZEB1, SNAI1, and OVOL1/2) represent IDPs and hypothesized that it is their conformational flexibility which enables the formation of highly dynamic protein interaction networks and phenotypic plasticity of cancer cells." (PMID 40889682, 2025). "Interestingly, there are no common genes between the ZEB1.mel and the ZEB1 pan cancer regulon." (PMID 38519642, 2024).
cancer (continued). "Additionally, considering the high co-expression between ZEB1 and FGD5-AS1 in pan-cancer and pan-tissue (p < 0.0001), we implied that the transcriptional regulation of FGD5-AS1 by ZEB1 may be widespread in human tissues and cancers." (PMID 38965605, 2024). "This evidence, together with our findings in the wound healing assay showing that integrin αvβ3 and ZEB1 mediate SPARC-induced migration, suggests that SPARC and some integrin genes could be positively and reciprocally regulated, contributing to the migration and invasion of cancer cells." (PMID 35682554, 2022). "Therefore, Zeb1 has the potential effect of promoting the canceration of non-cancer stem cells." (PMID 35611144, 2022). "Furthermore, the mutual inhibition between ZEB1 and AR may only be true for PCa cells, but not for other cancers." (PMID 33652914, 2021). "Also, many targeted genes, such as ZEB1, SOX5, AKAP1, CHP1, CNBP, VEGFR, and MAGT1, play a vital function in the cell shape, movement, invasion, adhesion, and polarity formation, so as to involve in many kinds of diseases such as malignant tumors, wound healing, and so on." (PMID 32547593, 2020). "In addition to enhancing cancer cell proliferation and survival, IL-6 induces EMT via JAK-STAT3 or NF-κB pathways, leading to the induction of several EMT-TFs such as Snail, Slug, Twist, and Zeb1, which suppress the expression of CDH1 via the recruitment of epigenetic regulators." (PMID 31557902, 2019). "In addition, miR-200c-3p and ZEB1 form a double-negative feedback loop that may contribute to the switch in the epithelial to mesenchymal transition in the development of cancer." (PMID 29095952, 2017). "In contrast, in malignant tumors with poor prognosis, n = 4, ITIH2 staining ranged from moderate in 50% of the samples (A, E) to absent in 50% (C, F), whereas ZEB1 showed strong intensity in all of these samples." (PMID 40005870, 2025). "ZEB1 is one of the most extensively studied molecules in the field of EMT and cancer cell differentiation, while ZEB2 has not been researched in depth." (PMID 39362647, 2024). "High mRNA levels of RKIP correlated negatively with those of SNAIL1, SNAIL2, TWIST1, TWIST2, ZEB1, and ZEB2 in several but not all carcinomas." (PMID 39335152, 2024). "While changes in expression of TGF-β, ZEB1, SNAI1, MMPs, vimentin, and E-cadherin are hallmarks of an EMT process occurring within cancer cells, including cSCC cells, EMT within tissues is not an “all or none” process." (PMID 36012449, 2022). "While Snail and Zeb1 constitute key EMT inducers, their relative transcript abundance in human cancer samples has not been well-studied." (PMID 34502497, 2021). "The direct interaction of ZEB1 with YAP (but not with TAZ) switches its function to an activator of a common ZEB1/YAP target gene set, known to stimulate cancer aggressiveness." (PMID 34439395, 2021). "During cancer progression, EMT is triggered by the interplay of specific secreted factors including EGF, PDGF, TGFβ; transcription factors such as ZEB1, Slug, Snail; and signal pathways such as AKT, ERK, and Notch." (PMID 34680255, 2021). "ZEB1, ZEB2, SNAI1, and TWIST1 drive EMT of cancer cells, but they are not required for metastasis in animal models." (PMID 34339740, 2021). "The direct interaction between ZEB1 and YAP, but not TAZ, stimulated the transcription of a ZEB1/YAP target gene set that is known to promote cancer aggressiveness." (PMID 31100975, 2019). "In accordance with ZEB1 deposition, considerable CD163+ TAMs infiltrated the stroma surrounding the hypoxic cancer cell islets but not the normoxic regions." (PMID 31263103, 2019). "The LuCSC-holoclones were EpCAM+ (morphologically epithelial), and negative for classical EMT genes AXL, CD10, Zeb1 and MMP1 that are involved in motility and invasive behavior of mesenchymal cancer cells." (PMID 31069016, 2019). "ZEB1 triggers a miR-200 family-mediated negative feedback loop that stabilizes EMT and promotes invasion of cancer cells." (PMID 25868853, 2015).
cancer (continued). "Consistent with MACE results, CTHRC1, TCF4 and ZEB1 were significantly higher expressed in PDAC compared to normal pancreas tissues, with median normalized Ct (ΔCt) values between −1.8 and 1.8 in cancer- and 3.1-5.1 in normal tissues." (PMID 25910082, 2015). "In panels of cancer cell lines including the NCI-60, ZEB1 expression showed a much stronger negative correlation with E-Cadherin expression than ZEB2, Slug, Snail or Twist." (PMID 24281177, 2010). "Therefore, both ZEB1 and ZEB2 proteins are inducers of cancer metastasis, and notably, their expression level is controlled by circRNAs in cancer." (PMID 38733529, 2024). "Thus, ZEB1/2 are positively correlated with EMT phenotypes and the aggressiveness of cancers, but SNAIL and Twist contribute to aggressiveness without mesenchymal phenotypes." (PMID 36140527, 2022). "We conclude that ZEB1-regulation of corneal NV is independent of VEGF and the ZEB1–CtBP inhibitors can be of potential therapeutic significance in treating ocular NV3, and likely cancers as well." (PMID 32620870, 2020). "With the close relationship between ZAK and ZEB1, ZAK may serve as an alternative target of ZEB1 that is thought non-druggable or difficult to target for cancer therapy." (PMID 29396440, 2018). "When we examined all non-hematopoietic cancer cell lines in the CCLE, we found that the degree of FLNB exon 30 splicing correlated significantly with a ZEB1 target signature, an epithelial differentiation signature, two metastasis signatures and a mammary stem cell signature." (PMID 30059005, 2018). "A double-negative feedback loop involving Zeb1/2 and microRNAs of the miR-200 family (miR-200a, miR-200b, miR-200c, miR-141, and miR-429) have been postulated to control epithelial–mesenchymal transition (EMT) in cancer cells." (PMID 30271956, 2018). "ZEB1 and ZEB2 have overlapping roles in cancer metastasis but there is evidence that they also have separate, non-redundant roles in development and cancer." (PMID 29963231, 2018). "An extra layer of intricacy was added to the equation when ZEB1 was found to directly suppress transcription of miR-141 and miR-200c, orchestrating a miRNA-mediated double negative feedback loop that stabilized EMT and promoted cancer cell invasion." (PMID 26784241, 2016). "Noteworthy, we corroborated the finding of GSDME fine-tuning by the ETAR/ZEB1 axis in breast (MDA-MB-231) and colon (SW620) cancer cell lines, both expressing ETAR, underscoring the ability of ET-1 to upregulate GSDME in the absence of macitentan and in a ZEB1-dependent manner." (PMID 41545335, 2026). "Therefore, we conclude that the regulation of corneal NV by Zeb1 is independent of VEGF and the ZEB1-CtBP inhibitor, NCS95397, may have the therapeutic potential for ocular NV and possible cancers." (PMID 38822380, 2024). "However, we did not observe a ZEB1-dependent effect on proliferation of CD8 + T cells in vitro when co-cultured with BMDMs, but a ZEB1-dependent modulation of CD8 + T cell migration by CCL2 and CCL22 as well as CCR2 and CCR4 expression in CD8 + T cell subsets in murine and human cancers." (PMID 40595293, 2025).
infection (34 papers, 2011 to 2025). The state of being infected such as from the introduction of a foreign agent such as serum, vaccine, antigenic substance or organism. "We show here that mice with Zeb1 deficiency in dendritic cells are more resistant to infection with Listeria monocytogenes, because of a selective reduction in splenic cDC1 population associated with excessive cell death." (PMID 37863917, 2023). "As already published by our team, infection with H. pylori was associated with a significant increase in ZEB1 and Ki67 proliferation marker in human gastric mucosa." (PMID 36077851, 2022). "In agreement with the total CAR protein and cell-surface CAR data, PANC-1 cells with silenced ZEB1 expression were more susceptible to infection with a green fluorescence protein (GFP)-encoding adenovirus (Ad-GFP) than the TGF-β treated non-silencing controls." (PMID 21791114, 2011). "There were 100 ~ 1000 times fewer CFU of bacteria in the spleen and liver of Zeb1-dcKO mice than in WT littermates at day 2 after infection with a low dose (2.5 × 104 CFU) of L. monocytogenes." (PMID 37863917, 2023). "The overexpression efficiency of ZEB1 was tested after 48 h of infection by real-time PCR and western blot analysis." (PMID 34109218, 2021). "The expression of the EMT markers Vimentin, ZEB1, and Snail, as well as the induction of the “hummingbird” phenotype after 24 h of infection, were also CagA-dependent, as previously reported." (PMID 32545795, 2020). "As described in the previous sections, infection of the oral mucosa by P. gingivalis leads to overexpression of EMT factors such as Zeb1." (PMID 31772577, 2019). "The sequential increase of Snail expression starting at 72 h post-infection followed by Zeb1 at 96 h is consistent with literature which demonstrates Snail expression precedes Zeb1expression in EMT." (PMID 29250491, 2017). "Infection of expanded islet cells with two different ZEB1 shRNA lentiviruses reduced ZEB1 protein levels by up to 85 ± 5%, while significantly elevating insulin transcript levels, relative to cells infected with a control shRNA." (PMID 26264186, 2015). "In AGS cells, both the pri-miR-200b RNA and ZEB1 mRNA start rising during the 2 to 4 hrs post-infection in a quite CagA-independent way, thus paralleling IL-8 changes." (PMID 23565224, 2013). "Treating the cells with anti-ZEB1 siRNA (siZEB1) before infection prevents both ZEB1 induction and mesenchymal morphology, contrarily to control siRNA (siControl)." (PMID 23565224, 2013). "In NCI-N87 cells, ZEB1 expression starts increasing at 4 hrs upon infection and quite independently of CagA." (PMID 23565224, 2013). "In MKN74 cells, ZEB1 starts rising at 6 hours post-infection independently on CagA, and the pri-miR-200b, E-cadherin and vimentin up-regulations were noticeable only at 24 hrs post-infection with the wt bacteria." (PMID 23565224, 2013). "ZEB1 protein accumulates in the nucleus upon infection, in agreement with its function as transcription factor." (PMID 23565224, 2013). "The mature miR-200b and -200c levels were significantly decreased in AGS and NCI-N87 cells, suggesting that these cell lines keep a track of their previous infection despite the apparent reversibility of ZEB1 up-regulation." (PMID 23565224, 2013). "miR-409-3p is known to target ZEB1, a major negative regulator of EBV lytic reactivation and infection, and TargetScan predicts that miR-381-3p may also target ZEB1)." (PMID 40674434, 2025). "These miRNAs then promote lytic infection, in part through downregulation of ZEB1." (PMID 40674434, 2025). "Furthermore, histological analysis showed that Zeb1-dcKO mice displayed substantially reduced lesions in the spleen and liver compared to WT littermates at day 2 after infection." (PMID 37863917, 2023).
infection (continued). "After 24 h infection, ZEB1 expression was increased and accumulated in the nuclei of the three cell lines, with a concomitant nuclear localization of TAZ, particularly visible in GC07 and MKN45 cells harboring the mesenchymal “hummingbird” phenotype at 5 h and 24 h post-infection." (PMID 32545795, 2020). "We speculate that it was due to adoptive transfer of CpG pulsed Zeb1 KD DCs that secrete suboptimal inflammatory cytokines, at D7 after infection." (PMID 30483264, 2018). "Analysis of Zeb1 mRNA levels in P. gingivalis infected and uninfected OECs reveal significantly increased expression in P. gingivalis-infected OECs beginning at 96 h-post-infection." (PMID 29250491, 2017). "However, miR-200b/c were increased upon infection, despite ZEB1 up-regulation and mesenchymal morphology." (PMID 23565224, 2013). "Finally, at 24 hrs post-infection, all the markers were up-regulated: the pri-miR-200b and ZEB1, along with IL-8, by both wt and the CagA-deleted strain, E-cadherin and vimentin by the wt bacteria only." (PMID 23565224, 2013). "ZEB1 restoration resulted in a ~ 25% increase in cell viability in BGC823, as compared with the same cells after infection with the Lenti-LV201 control." (PMID 40092690, 2025). "All WT mice succumbed to infection with a high dose (1 × 106 CFU) of L. monocytogenes, whereas almost all Zeb1-dcKO mice survived." (PMID 37863917, 2023). "The infection rates were about 80% based on the GFP expression of the cells for both vector control (Vect Ctrl) and ZEB1-KD cells (ZEB1sh) before the first passage (P0)." (PMID 37081200, 2023). "Prolonged infection of P. gingivalis promotes migratory and invasive properties in epithelial cells, inducing the expression of matrix metalloproteinase and epithelial–mesenchymal transition (EMT) transcription factors such as SNAIL, SLUG, and ZEB1." (PMID 38539520, 2024). "In spite of incomplete gene deletion using the Mx-Cre system, we also identified Zeb1 as a regulator of CD8+ EM in BM and PB and CD8+CM T cells from spleen, supporting previous observations that Zeb1 is critical to CD8+ T cell function during infection." (PMID 33108352, 2021). "This suggests that MDV and possibly other herpesviruses induce a ZEB1/miR-10b negative feedback loop to create a more favorable environment for a productive infection." (PMID 30764490, 2019). "To validate ZEB1 and PDGFRA as miR-200 and/or miR-34 targets in a PGL cell context, we enforced miR-200 (LV-200ab/429) or miR-34 (LV-miR-34bc) overexpression by lentiviral infection in PTJ64i cells." (PMID 29305721, 2018). "Thus, we measured E‐cadherin levels in MOC1 cells after infection with lentiviruses carrying ZEB1 (MOC1‐ZEB1 cells), ZEB2 (MOC1‐ZEB2 cells), Snail, or a negative control (hereafter referred to as MOC1‐NC cells)." (PMID 39362647, 2024). "The authors further characterized the chlamydial EMT phenotype via an in vitro model of infection using primary epithelial cells of the murine oviduct, revealing infection-dependent repression of E-cadherin and induction of SNAIL1/2, fibronectin, and ZEB1 via immunofluorescence." (PMID 37265500, 2023). "Similarly, treatment of HSV-1 infected cells with proteasome inhibitor MG132 added after the onset of the infection was sufficient to stabilize ZEB1, but interestingly not ZEB2, in the presence of HSV-1 expressing either wild type ICP0 or the FXE mutant." (PMID 28783105, 2017). "ZEB1 and AP1 have been shown to be involved in HIV latency and NFATC2 is essential for productive infection of non-activated T-cells." (PMID 35513551, 2022). "The mesenchymal marker vimentin/VIM was repressed by infection (FC, −2.22), whereas common markers of EMT (e.g., CDH1/2, SNAI1/2, and ZEB1/2) were not differentially expressed, suggesting that infection does not induce EMT in endocervical epithelial cells at 24 hpi." (PMID 37874141, 2023).
infection (continued). "Infection with 5 MOI of EpCAM-WT lentiviral particles did not affect E-cadherin expression; however, dose dependent treatments of 2, 5, and 10 MOI of EpCAM-L240A lentiviral particles induced ZEB1 and vimentin expression and suppressed E-cadherin expression." (PMID 37192201, 2023). "The results revealed that the miR-200c overexpression in the tumors led to a marked reduction of ZEB1 mRNA, Vimentin mRNA and the protein expressions compared with the CD44+CD117+CSCs with lentivirus mock and with the CD44+CD117+CSCs without lentivirus infection." (PMID 23842108, 2013).